XRCC4 (X-ray repair cross complementing 4)
Diseases named in the same sentence as XRCC4 in open-access papers (continued):
Sharing a sentence is not in itself a finding about the gene and the disease.
tumor (continued). "Comparison of the methylation levels in LUAD tumor tissues with those in normal tissues identified three relevant methylation sites each in XRCC4 and XRCC5 (P < 0.05), whereas no such methylation sites were found in XRCC6 (P < 0.05)." (PMID 34486486, 2021). "Our analysis revealed elevated levels of XRCC4 mRNA in Oncomine and protein data analysis, respectively, whereas the comparison of expression between paired normal and tumor tissues in TCGA dataset did not exhibit a significant difference in XRCC4 expression." (PMID 33195430, 2020). "Consistent with the Oncomine analysis, comparison of all available normal (n = 41) and tumor tissues (n = 469) revealed overexpression of XRCC6, XRCC5, PRKDC, XRCC4, and PAXX in tumors compared to normal tissues, while LIG4 and NHEJ1 displayed lower expression in the tumor tissues." (PMID 33195430, 2020). "Interestingly, many of these genes are known to be involved in cell-cycle function (CDK2, CDK6, CCNB1, CEP55, CENPF), transcriptional regulation/tumor suppression (FOXO3, TOP2A), DNA-damage response (ASPM, XRCC4), and tumor progression (CYR61, MACC1, CXCR4)." (PMID 28482906, 2017). "Noteworthy, XRCC4 expression was significant positive correlated with infiltration levels of CD4+ T cells, CD8+ T cells, dendritic cells, macrophage, and neutrophil, which infiltrated in TME have been known as both anti- and pro-tumor properties promote immunosuppression in tumor immune escape." (PMID 36765282, 2023). "Interestingly, in contrast to Oncomine analysis, XRCC6 and XRCC4 did not display differential expression between paired normal and tumor tissues (respectively)." (PMID 33195430, 2020). "MCPyV integration within cellular genes could also act as a mechanism of tumor suppressor gene inactivation in a subset of tumors, as potentially disruptive integration into genes with tumor suppressor roles (PTPRG, XRCC4) has been described in individual cases." (PMID 32878339, 2020). "FBXW7 promotes ubiquitination of XRCC4 via lysine 63 linkage to facilitate nonhomologous end-joining, rather than proceeds to XRCC4 degradation, while these two pathways of ubiquitination (via K48 and K63 linkage) contribute to the tumor suppressor role of FBXW7 together." (PMID 28422719, 2017). "In contrast, significantly lower mRNA expression in tumor samples with high CIN70 score was observed for SMC1 (**), ERCC1 (***) and LIG4 (****), and a non-significant for XRCC4 (n.s.)and BOD1L1 (n.s.)." (PMID 33801877, 2021). "For most sections with high tumor cell density, both UHRF1 and XRCC4 are highly expressed in an indistinguishable manner." (PMID 29415984, 2018). "As immunostaining does not allow for a collective analysis for the whole tumor tissues, we used fresh tumor lysates to examine the expression level of UHRF1, XRCC4, and a few apoptosis markers." (PMID 29415984, 2018).
infection (5 papers, 2011 to 2021). The state of being infected such as from the introduction of a foreign agent such as serum, vaccine, antigenic substance or organism. "A DNA repair complex of DNA ligase IV and XRCC4 circularizes herpes simplex virus genomes early in infection." (PMID 21589897, 2011). "At the same time, upregulation of key components that catalyze end-processing and ligation, namely, RAD50, ARTEMIS, XRCC4, and LIG4, was observed upon infection." (PMID 33339161, 2020). "DNA LIG4 and XRCC4 promote HSV-1 replication, while DNA-PKcs and the Ku heterodimer restrict infection." (PMID 29144403, 2017). "Although other steps from initial infection to eventual viral genome integration could still be affected by RIG-I, we think its inhibitory role on XRCC4 and NHEJ is a major factor, given the key role of NHEJ in viral integration into the genome." (PMID 33846346, 2021).
genetic disorder (2 papers, 2014 to 2016). "Along with other genes, such as Artemis, X-Ray Repair Cross-Complementing Protein 4 (XRCC4), Protein Kinase DNA activated Catalytic Polypeptide (PRKDC), and NHEJ1, encoding V(D)J/NHEJ proteins, it has been found to be deficient in human genetic disorders." (PMID 27855655, 2016).
XRCC4 also shares sentences with these, for which no sentence is quoted: lung carcinoma (5 papers); brain tumors (4); cardiomyopathies (2); colorectal (2); osteosarcoma (2); severe combined immunodeficiency (2); acute lymphoblastic leukemia (1); adenocarcinoma (1); adrenocortical carcinoma (1); anemia (1); cardiac failure (1); cerebellar ataxia (1); colitis (1); colon adenocarcinoma (1); developmental delay (1); diffuse large B-cell lymphoma (1); Fanconi anemia complementation group C (1); gastrointestinal stromal tumor (1); head and neck squamous cell carcinoma (1); infectious disease (1); infertile (1); LIG4 syndrome (1); liver cancer (1); lung adenocarcinoma (1); lung squamous cell carcinoma (1); lupus (1); lymphoid neoplasm (1); lymphopenia (1); metastasis (1); mucinous adenocarcinoma (1).
A further 10 diseases each share a sentence with XRCC4 in 1 paper.